GIPC2 (GIPC PDZ domain containing family member 2)
Synonyms: FLJ20075; SEMCAP-2; SEMCAP2
Tractability: Small molecule: it has a binding pocket of medium quality. PROTAC: its protein half-life has been measured.
Gene: Protein-coding gene on chromosome 1 (77,979,542 to 78,138,448, forward strand). Ensembl gene ENSG00000137960.
Subcellular location: Cytoplasm
Subcellular location (Human Protein Atlas): Nucleoplasm; Cytosol
Gene Ontology:
Molecular function: identical protein binding; protein binding
Cellular component: cytosol; extracellular exosome; cytoplasm
Genetic constraint (gnomAD): Loss-of-function variants: 11 observed, 7.68 expected, observed/expected ratio (o/e) 1.43, 90% interval 0.88 to 1.92. That is too few expected variants to judge how well the gene tolerates losing a copy. Missense variants: 172 observed, 128.26 expected, observed/expected ratio (o/e) 1.34, 90% interval 1.18 to 1.52. Synonymous variants: 80 observed, 57.61 expected, observed/expected ratio (o/e) 1.39, 90% interval 1.16 to 1.67.
Homologues: Orthologues: chimpanzee GIPC2 (98% identical), pig GIPC2 (86% identical), rat Gipc2 (84% identical), mouse Gipc2 (83% identical), dog GIPC2 (77% identical), macaque GIPC2 (74% identical), tropical clawed frog gipc2 (69% identical), rabbit GIPC2 (68% identical), zebrafish gipc2 (68% identical), guinea pig GIPC2 (65% identical), Drosophila melanogaster kermit (47% identical), Caenorhabditis elegans gipc-1 (35% identical), and 1 more. Paralogues in human: GIPC1 (63% identical), GIPC3 (54% identical).
Diseases named in the same sentence as GIPC2 in open-access papers:
GIPC2 is named in the same sentence as 16 diseases in open-access papers, as found by Europe PMC text mining. Sharing a sentence is not in itself a finding about the gene and the disease. The quoted sentences say what the papers report.
prostate carcinoma (4 papers, 2022 to 2024). A carcinoma that arises from epithelial cells of the prostate gland. "However, a recent work has found GIPC2 was upregulated in prostate cancer and promoted the tumor metastasis through activating WNT signaling." (PMID 36281556, 2023). "In addition, as well as being a component of exosomes, the GIPC2 paralog plays a key role in WNT signaling pathways associated with tumor progression and was shown to be robustly stimulating the adhesion, invasion, and migration of prostate cancer." (PMID 37965478, 2023).
acute lymphoblastic leukemia (2 papers, 2022 to 2025). Leukemia with an acute onset, characterized by the presence of lymphoblasts in the bone marrow and the peripheral blood. "Indeed, GIPC2 is upregulated in gastric cancer, but downregulated in kidney cancer, adrenocortical carcinoma, and acute lymphocytic leukemia (ALL)." (PMID 35347223, 2022). "In cancers like acute lymphoblastic leukemia (ALL), GIPC2 is silenced through promoter hypermethylation, suggesting an epigenetic mechanism of downregulation." (PMID 40933995, 2025).
breast carcinoma (2 papers, 2025). "This aligns with findings from other cancers, including gastric and breast cancer, where GIPC2 promotes tumorigenesis." (PMID 40933995, 2025).
gastric cancer (2 papers, 2008 to 2025). A primary or metastatic malignant neoplasm involving the stomach. "• GIPC2 mRNAs are expressed in cells derived from a diffuse-type of gastric cancer, and also shows increased expression in several cases of primary gastric cancer." (PMID 18837980, 2008).
colorectal cancer (1 paper, 2024). A primary or metastatic malignant neoplasm that affects the colon or rectum. "Whole-genome sequencing revealed the presence of missense mutations F74Y and R312Q, as well as a nonsense mutation E216X, in GIPC2 in colorectal cancer." (PMID 39399504, 2024).
colorectal tumors (1 paper, 2015). "The GIPC2 gene was reported to be down-regulated in human primary kidney and colorectal tumors." (PMID 26283601, 2015).
Infertility (1 paper, 2019). "Furthermore, gipc-1;gipc-2 and spe-15(qx529) affected spermatid activation in vitro and caused infertility due to defects in spermatids." (PMID 30990821, 2019).
malignant melanoma (1 paper, 2025). "Previous studies have demonstrated that the missense mutations D125N and E288K in GIPC2 were implicated in malignant melanoma development." (PMID 41468441, 2025).
metastatic tumors (1 paper, 2022). "Western blotting measured normalized, urinary GIPC2 protein levels in samples from our cohort of 46 patients (31 primary and 15 metastatic tumors from bones)." (PMID 35347223, 2022). "The area-under-the-curve (AUC) values for GIPC2 were 0.953 (95% confidence interval [CI], 0.75–0.95; sensitivity, 83.3%; specificity, 83.3%) and 0.80 (95% CI, 0.899–1.007; sensitivity, 86.7%; specificity, 90.3%) for the primary and metastatic tumors, respectively." (PMID 35347223, 2022).
pheochromocytoma-paraganglioma (1 paper, 2022). A rare neuroendocrine tumor arising from chromaffin cells of the adrenal medulla (pheochromocytoma) or from sympathetic and parasympathetic ganglia (paraganglioma). "In pheochromocytoma/paraganglioma (PPGL), we previously demonstrated that GIPC2 is a tumor suppressor with loss of function triggering tumorigenesis via loss of heterogynous at GIPC2 locus and hypermethylation of GIPC2." (PMID 35347223, 2022).
cancer (7 papers, 2011 to 2026). A tumor composed of atypical neoplastic, often pleomorphic cells that invade other tissues. "In addition, several of the promoter-hypermethylated genes were associated with the development of human cancers and these include GIPC2, DIRAS3, TYSPL6, EDNRB, FYN, GDNF, RASSF1, and RASSF2." (PMID 21962230, 2011). "Despite its well-characterized functions in cancer, the role of GIPC2 in stem cell biology remains largely unexplored." (PMID 41500998, 2026). "On the contrary, we noted the role of GLO1, HOOK1, and GIPC2 was rarely investigated in CRC but well identified in other cancers." (PMID 36281556, 2023). "Since GIPC2 as a hub gene of the signature was poorly investigated in cancers, we next made efforts to clarify its role in CRC." (PMID 36281556, 2023). "Further studies should focus on identifying ligands of the PZD domain in GIPC2 for different cancer types." (PMID 35347223, 2022). "Furthermore, many of the processes influenced by GIPC2 in cancer—such as plasticity and metabolic adaptation—are also crucial for stem cell behavior, particularly in self-renewal, differentiation, and lineage commitment." (PMID 41500998, 2026). "This analysis showed weak cancer cell metastasis in the liver of the GIPC2-knockdown group." (PMID 35347223, 2022). "GIPC2 induced p27, suppressed MAPK/ERK and HIF-1ɑ pathways as well as cancer cell proliferation." (PMID 33947839, 2021). "Indeed, our observation of GIPC2 abnormal methylation as well as higher GIPC2 expression in mPCa suggests that GIPC2 activation rather than inactivation is favorable for cancer formation." (PMID 35347223, 2022).
tumor (6 papers, 2021 to 2026). "Among these isoforms, GIPC2 has been most extensively studied in the context of tumor biology, where it has been implicated in regulating key processes such as EMT, metabolic reprogramming, and cell survival." (PMID 41500998, 2026). "Moreover, using a microfluidic array, we demonstrated that GIPC2 deficiency dramatically restricted tumor cell invasion and migration, accompanied by WNT-β-catenin-pathway activation." (PMID 35347223, 2022). "GIPC2 is a GIPC1 paralog involved in WNT signaling pathways associated with tumor progression, but its role in PCa metastasis remains unclear." (PMID 35347223, 2022). "While the preceding studies established the tumor-suppressing role of GIPC2 in sporadic PPGLs, we further explored whether GIPC2 had a role in RET mutation-related hereditary PPGL, since all 7 RET-mutated cases in our cohort had GIPC2 loss." (PMID 33947839, 2021). "GIPC2 has been predominantly studied in the context of tumor biology, where it regulates vital processes such as epithelial–mesenchymal transition (EMT), metabolic reprogramming, and cell survival." (PMID 41500998, 2026). "Our findings show that GIPC2 is upregulated in CRC tumor tissues, which correlates with increased cell proliferation, migration, and invasion, suggesting that it functions as an oncogenic driver in CRC." (PMID 40933995, 2025). "Our finding is consistent with a recent study proving GIPC2 inhibited the tumor growth through regulating p27 transcription." (PMID 36281556, 2023). "Meanwhile, our study for the first time demonstrates GIPC2 serves as a tumor suppressor through inhibiting EMT in CRC cells." (PMID 36281556, 2023). "The presence of GIPC2 in tumor-derived exosomes and ability to impact the behavior of tumor cells suggest that GIPC2 is a novel epigenetic oncogene involved in PCa metastasis." (PMID 35347223, 2022). "In contrast to the role of GIPC2 as a putative tumor suppressor in ALL and PPGLs, the potential oncogenic function of GIPC2 in PCa demonstrated a cell-type dependent function." (PMID 35347223, 2022). "Increased RWPE-1 cell adhesion, invasion, and migration were observed when cells were treated with exosomes from GIPC2-high expression tumor cells versus control exosomes." (PMID 35347223, 2022). "GIPC2 encodes a 315-amino acid protein that is 62% identical to GIPC1 and is considered a paralog of GIPC1 that promotes proliferation and invasion in tumor metastasis." (PMID 35347223, 2022). "Upregulation of GIPC2 acts as a oncogene that promotes cell proliferation and survival, whereas downregulation of GIPC2 acts as a tumor suppressor." (PMID 35347223, 2022). "This is the first study indicating that GIPC2 promotes tumor metastasis independently of cell proliferation and apoptosis through the WNT–β-catenin pathway, and is thus promising as a novel drug target." (PMID 35347223, 2022). "Subsequently, a subcutaneous transplantation tumor model in nude BALB/c mice also confirmed the tumor suppression role of GIPC2 in tumor growth in vivo." (PMID 33947839, 2021). "To further explore the molecular mechanism of tumor suppression by GIPC2, we used immunoprecipitation-mass spectrometry to identify GIPC2 interaction partners." (PMID 33947839, 2021). "We present evidences that GIPC2 upregulates p27 and suppresses PPGL cell proliferation and tumor growth both in vitro and in vivo, and we propose a GIPC2-based mechanism through which sporadic and RET- and SDHB-related hereditary PPGLs develop." (PMID 33947839, 2021). "On the other hand, SDHB-mutated cells proliferate in extra-adrenal to form tumors by virtue of downregulating GIPC2, while in the adrenal the proliferation is countered by glucocorticoid-induced GIPC2 and tumor seldom forms." (PMID 33947839, 2021). "Therefore, extensive work is still needed to clarify the role of GIPC2 in tumor initiation and development." (PMID 36281556, 2023).
tumor (continued). "Furthermore, GIPC2 promoter hypermethylation has been detected in patients and cell lines, consistent with its suggested potential role as an epigenetic tumor suppressor in ALL." (PMID 35347223, 2022). "Overexpressing GIPC2 in PC12 cells inhibited tumor growth in nude mice." (PMID 33947839, 2021). "Western blot also confirmed the significantly reduced GIPC2 protein levels in tumor tissues." (PMID 33947839, 2021). "In this study, using high-resolution microarrays and selecting for genes with preferential expression in adrenal, we identified a novel tumor suppressor gene GIPC2, that was inactivated in a majority of sporadic PPGL tumors due to copy number deletion and promoter hypermethylation." (PMID 33947839, 2021). "Indeed, in PCa, GIPC1 as a paralogous gene of GIPC2—which is involved in endosomal signaling and tumor cell proliferation, invasion, and metastasis —the PDZ domain of DVL binds the C-terminal region of Fzd receptors and is essential for WNT-signal transduction in PCa tumorigenesis." (PMID 35347223, 2022). "Next, we tested whether tumor-derived, GIPC2-positive exosome treatment affected PCa cell motility." (PMID 35347223, 2022). "To explore the functional role of GIPC2 in CRC, we quantified its mRNA expression in paired CRC and adjacent normal tissues by qRT-PCR, finding a significant upregulation in tumor tissues." (PMID 40933995, 2025). "We found GIPC2 was downregulated in CRC tissues and most CRC cell lines, implying its role as a tumor suppressor." (PMID 36281556, 2023). "We observed low GIPC2 expression in localized tumors or the normal prostate cell line, RWPE-1, and increased expression in metastatic tumor or cell line." (PMID 35347223, 2022). "In tumor tissue homogenates from mouse xenografts, protein expression of GIPC2, p-GSK-3β, and activated β-catenin were measured to verify the effects of GIPC2." (PMID 35347223, 2022). "These interactions, if validated in CRC, could position GIPC2 as a central player in the hypoxic TME, further promoting tumor aggression and metastasis." (PMID 40933995, 2025). "Furthermore, tumor metastasis was increased by GIPC2 overexpression, but not by GIPC2-PDZ deletion." (PMID 35347223, 2022).
metabolic disorders (1 paper, 2026). "By acting as a facilitator of PKM2-SREBP1 signaling, GIPC2 may serve as a potential therapeutic target for modulating adipogenic differentiation and treating metabolic disorders." (PMID 41500998, 2026).
GIPC2 also shares sentences with these, for which no sentence is quoted: lung carcinoma (1 paper); paraganglioma (1); pheochromocytoma (1).